BRAF (B-Raf proto-oncogene, serine/threonine kinase)
Diseases named in the same sentence as BRAF in open-access papers (continued):
Sharing a sentence is not in itself a finding about the gene and the disease.
cancer (continued). "BRAF inhibitors and anti-CTLA-4 and anti-PD-1 monoclonal antibodies are changing the landscape of cancer treatments." (PMID 25660021, 2015). "Using siRNAs, we attempted to knock-down the expression of the two amplified, predicted driver genes in the cell line (BRAF and TRIM24) and noted a substantial reduction in the proliferation rate of cancer cells for both genes." (PMID 25572314, 2015). "However, there was no synchronous carcinoma found in BRAF-mutated patients in our study." (PMID 25929517, 2015). "Second, our pipeline was able to recapitulate most known translocation events in cancer (ALK, BRAF, EGFR, FGFR1, 2 and 3, NTRK1, 2 and 3, PDGFRA, PRKCA, RAF1, RET, ROS1)." (PMID 25204415, 2014). "KRAS, NRAS, HRAS, BRAF, PIK3CA, PIK3R1 and PTEN are key cancer-related genes in the RAS/RAF and PI3K/PTEN signaling pathways." (PMID 25120700, 2014). "We have previously found comparably high frequencies of LOH events between BRAF mutant/MSS cancers and BRAF wild type cancers at several key genomic loci (18q, 17p, 5q and 8p), that are known to harbour important tumour suppressor genes." (PMID 24651849, 2014). "Since arriving on the market in 2011, the Ion Torrent PGM, a benchtop sequencer, has already been successfully used for the targeted resequencing of cancer genes, such as BRCA, BRAF, POLE and POLD1." (PMID 24705691, 2014). "In cancer models: BRAF and RAS oncogenes are considered to induce cancer properties by regulating similar signalling pathways." (PMID 25361007, 2014). "In an analysis of 24 breast tumours, rearrangements were found in known cancer genes including BRAF, PAX3, PAX5, NSD1, PBX1, MSI2 and ETV6, each of which is a partner in a fusion gene in several other human cancers." (PMID 24792170, 2014). "The majority of BRAF mutant cancers derived from the proximal colon, whereas most BRAFwt/MSS cancers were found distally (p<0.0001)." (PMID 24651849, 2014). "Similar findings for EREG high vs. low were seen when we examined complex cancer genotypes: a) KRAS+BRAF, both wild type vs. any mutant, b) KRAS+BRAF+PIK3CA+NRAS, all wild type vs. any mutant." (PMID 23374602, 2013). "Similar arguments can be made about other inhibitors to key molecular targets such as BRAF or EGFR, PARP, and COX-2, thereby emphasizing the importance of such molecules in gene-specific target cancer therapy." (PMID 24040001, 2013). "However, it is clear that certain papillary cancer foci may have the same origin since there are mutlifocal carcinomas with homogeneous distributions of BRAF mutations or lacking BRAF mutations." (PMID 23599804, 2013). "These important results were obtained by performing washout studies in vitro and alternate dosing schedules in mice with MEK and PI3K inhibitors with BRAF and KRAS mutant cancer cells." (PMID 23085539, 2012). "In addition, activating mutations in BRAF, a member of the RAF gene family, which encode kinases that are regulated by members of the RAS protein family (HRAS, KRAS, and NRAS) and mediate cellular responses to growth signals, were found to be associated with microsatellite instability (MSI) cancers." (PMID 22931052, 2012). "The effects of combining GDC-0973 and the PI3K inhibitor GDC-0941 on the proliferation of BRAF and KRAS mutant cancer cells indicated combination efficacy both in vitro and in vivo." (PMID 23085539, 2012). "Although similarly high rates of CIN were observed in BRAF mutant and wild type MSS cancers, differences existed between the two cohorts regarding the chromosomal regions most commonly targeted, and the stages of presentation at which CIN was most frequent." (PMID 23110075, 2012). "Immediate effects of siRNA on SK-BR-3 growth on the Test Cancer Biochip were observed at day 2 for ERBB2, ESR2, CSK, CTSL2, and BRAF siRNAs." (PMID 23049944, 2012).
cancer (continued). "Indeed, activating KRAS, BRAF and PIK3CA mutations are able to bypass EGFR pharmacological inhibition, thereby resulting in a constitutive activation of the mitogen-activated protein kinase and AKT pathways, known to play a central role in cancer onset and progression." (PMID 22911782, 2012). "Two recent studies demonstrate interesting relationships between cancer oncogenes (KRAS, BRAF and ErbB2), regulation of glucose transport and cell survival under conditions of stress." (PMID 21826239, 2011). "The biomarker panel was additionally positive in 111/121 (92%) cancers harboring the MSS/MSI-low phenotypes and wild-type BRAF." (PMID 21777459, 2011). "In contrast to BRAF oncogene, RAS has been widely studied concerning its cooperation with Rho GTPases in cancer progression." (PMID 21943101, 2011). "Two other kinase-dead BRAF mutants, the classical catalytic lysine mutant (K483MBRAF), and D594VBRAF, a mutant found in human cancer, also activate MEK in D04 cells." (PMID 20141835, 2010). "Eligible studies included prospective and retrospective trials as well as cohort studies assessing BRAF inhibitors in non-melanomatous cancers." (PMID 42277540, 2026). "Functionally, oncogenic BRAF drives persistent activation of the MAPK/ERK pathway, which attenuates upstream EGFR/RAS signaling and thereby perturbs antitumor immune surveillance at multiple stages of the cancer-immunity mechanisms." (PMID 41596586, 2026). "Applied to LUAD and LUSC datasets, our approach successfully identified a stable core set of pathogenic genes, including both highly expressed genes (e.g., CD74, HGF) and stably expressed genes (e.g., BRAF, KDM6A), which play critical roles in cancer progression." (PMID 40136480, 2025). "To our knowledge, RAF dimerization studies evaluating pan-RAF inhibitors in various BRAF-mutant cancer cells have not been reported; beyond demonstrating MOA, we aimed to also address this knowledge gap." (PMID 41282105, 2025). "In addition, we analyzed the expression of BRAF, MEK, and PI3K in pan-cancer on PANDA, with a particular interest in their expression levels in CRC." (PMID 41009348, 2025). "Considering that interference with PAK1 function makes at least some BRAF- and RAS-driven cancer cells more vulnerable to the inhibitors of the MAPK cascade, we tested whether inhibition of RAC would have a similar effect." (PMID 41465386, 2025). "Neither of the mutations identified in our patients (BRAF p.V600E or HRAS p.G13R) has been previously published in DICER1-associated malignancies, despite being bona fide driver mutations in other cancers." (PMID 40634537, 2025). "Their clinical relevance in gastric and colon cancers stems from their frequent dysregulation, often driven by genetic alterations (e.g., KRAS, BRAF, PIK3CA, PTEN, and mTOR), which leads to constitutive activation and fosters uncontrolled cancer cell growth and survival." (PMID 40729043, 2025). "The basis for elevated RAS pathway activation in TPM cancers is not always obvious, as many of these tumors lack hyperactivating mutations in key RAS pathway effectors such as BRAF." (PMID 40560846, 2025). "Among patients with isolated BRAF mutation (n = 29, 90.6%), 66% of tumors were ATA low-risk cancers, 35% were benign, and none were high-risk cancers." (PMID 40075589, 2025). "Dabrafenib and trametinib, inhibiting BRAF and MEK proteins, respectively, have shown durable responses and manageable toxicity in treating not only melanoma but also other BRAF-positive solid tumours, such as NSCLC, anaplastic thyroid cancer (ATC), and various other cancers." (PMID 40141188, 2025). "Using gene essentiality score across a large panel of cancer cell lines, we found that BRAFV600E-driven cancers are highly sensitive to TAZ loss, unlike their counterparts with wild-type BRAF and non-BRAFV600E." (PMID 40667288, 2025).
cancer (continued). "Unlike canonical oncogenes, like BRAF or KRAS, FOXM1 is not commonly mutated nor amplified in cancer, warranting its exclusion from common “cancer gene lists” such as the Sanger Institute’s COSMIC Cancer Gene Census." (PMID 39858603, 2025). "Oncogenic BRAF class III kinase-impaired mutations were identified in two patients with refractory cancer, while none were found in patients with sensitive cancer." (PMID 40885189, 2025). "We found 6 significant gene-cancer type pairs impacted by CNAs where samples also contained eccDNA copies of the gene, including PIK3CA in BRCA, KRAS in COAD and LUAD, BRAF in SKCM, and EGFR in LUAD." (PMID 41415395, 2025). "For example, the observed increased sensitivity of BRAF/PIK3CA double-mutant cell lines to AZ628 raises the hypothesis that combined inhibition of RAF and PI3K pathways could be explored in cancers harboring these alterations." (PMID 41340127, 2025). "This analysis also helps in identifying the proper mutations, here BRAFV600E, for highly specific treatments (such as the BRAF inhibitor vemurafenib) that only target cancer cells and will not affect healthy cells and thereby improve a patient’s condition." (PMID 40277531, 2025). "A significant difference in dependency based on copy number status was also observed in the non-mutated cell lines for KRAS, but not for BRAF, suggesting that for KRAS also increasing the non-mutated copy number is beneficial for the cancer cells." (PMID 40694850, 2025). "MEK1 and PKD3 have been reported as potential therapeutic targets for BRAF-mutant carcinomas and estrogen receptor-negative breast cancer, respectively." (PMID 40737275, 2025). "Somatic genetic variations in APC, KRAS, BRAF, and PIK3CA genes are the most frequent in CRC, leading to the activation of key WNT–β-catenin and MAPK signal transduction pathways, which subsequently promote cell proliferation and cancer progression." (PMID 37863651, 2024). "Additionally, other hotspots have also been studied in specific cancers, such as IDH1 and IDH2 in gliomas, EGFR in the lung, and BRAF in skin cancer." (PMID 38473427, 2024). "There is evidence suggesting that BRAF and MEK inhibition induces CD4 and CD8 T lymphocytes, boosting their cytotoxicity against cancer cells, which is evident by elevated granzyme B and perforin levels, and an elevated expression of cytotoxic T-lymphocyte-associated protein-4 (CTLA-4)." (PMID 38731852, 2024). "This meta-analysis aimed to assess the impact of the most relevant molecular alterations in cancer-related genes of CRC (i.e., RAS, BRAF, SMAD4, PIK3CA) as prognostic markers of survival and disease recurrence in patients with mCRC surgically treated by LM resection." (PMID 39220128, 2024). "Moreover, numerous oncogenic drivers (ALK, BRAF, EGFR, MET, NRG1, NTRK1/2/3, RET, and ROS1) involved in sole reciprocal fusions were found in those cancers." (PMID 39254060, 2024). "Herein, we describe the biological and preclinical characterization of IAG933 and its close analogs, their monotherapy activity in specific Hippo-dependent cancers and in combination with receptor tyrosine kinases (RTKs), KRAS, BRAF, MEK or ERK inhibitors in a broad range of other cancer models." (PMID 38565920, 2024). "Notably, the BRAF inhibitor (BRAFi) and MEK inhibitor (MEKi) combination has received approval from the US Food and Drug Administration (FDA) for various cancer types." (PMID 38655260, 2024). "All types of carcinomas that were negative in the BRAF immunohistochemistry were further investigated by performing a ddPCR from their TMA block as a pool sample." (PMID 39591358, 2024).
cancer (continued). "The targeted agents cetuximab and panitumumab, combined with chemotherapy, are an effective treatment for metastatic colon cancer, provided that certain mutations have not occurred in cancer cells (namely activating mutations in KRAS, NRAS or BRAF genes)." (PMID 37686636, 2023). "BRAF (v-raf murine viral oncogene homolog B1), a member of the RAF family of serine/threonine protein kinases that signal to MEK-ERK kinases, has been identified as an oncogene driver in multiple cancers." (PMID 36854806, 2023). "UG-FNAB and BRAF p.V600E genetic testing have been used in Qilu Hospital, but their effect on the incidence of malignant tumors during surgery in the past 10 years is not clear." (PMID 36070149, 2023). "This review further highlights promising targets like mesenchymal-epithelial transition (MET), ROS1, BRAF, and poly(ADP-ribose) polymeras (PARP) in specific cancer subsets, along with ongoing clinical trials that continue to shape the future of targeted therapy." (PMID 37686423, 2023). "Functional studies using human cancer cell lines have shown that, in contrast to V600E mutants, ∆NVTAP mutants are resistant to BRAF monomer inhibitors such as vemurafenib and dabrafenib that target the ‘αC-out/DFG-in’ structural conformation of the active protein kinase." (PMID 37079639, 2023). "It is noteworthy that the rs12028023 A‐allele specifically improved survival in patients with KRAS and NRAS mutant cancers, but not in those with BRAF mutant cancers, supporting a direct effect on the upstream RAS signaling pathway." (PMID 36790221, 2023). "Vemurafenib (PLX4032), a small-molecule inhibitor of BRAFV600E kinase, has high specificity for the BRAFV600E oncoprotein and exhibits a potently inhibitory effect on the MAPK/ERK cascade in BRAF-mutant cancer cells, but not BRAF wild-type cells." (PMID 36834830, 2023). "Patients with rare cancers more frequently had CDKN2A and BRAF genetic alterations compared to patients with non-rare cancers, leading to more matches with CDK4/6 inhibitors (14% vs. 4%; p ≤ 0.001) or BRAF inhibitors (9% vs. 1%; p ≤ 0.001)." (PMID 37046628, 2023). "Combinations with dabrafenib (BRAF inhibitor), trametinib (MEK kinase inhibitor), and pembrolizumab (humanized antibody for cancer immunotherapy) are now in use with rosuvastatin (HMG-CoA reductase inhibitor (statins)) or BP-101 (polyamine metabolic inhibitor) against multiple cancers." (PMID 37762231, 2023). "Interestingly, pan-cancer analysis showed that MYC amplification is mutually exclusive with many canonical oncogenic drives such as PIK3CA, PTEN, APC, and BRAF." (PMID 37601651, 2023). "Patients with rare cancers treated with off-label BRAF inhibitors had a 75% clinical benefit rate, higher than the non-rare cancer group." (PMID 37046628, 2023). "This can be anticipated as BRAF and KRAS are mutually exclusive in most cancers." (PMID 37404765, 2023). "Unlike other components of the MAPK pathway, such as KRAS, BRAF, and NRAS, MRAS has not been found to be mutated in human cancers, and perhaps this circumstance has excluded it from being an attractive anticancer target." (PMID 37996408, 2023). "STIT employs drugs such as BRAF inhibitors (dabrafenib, vemurafenib, encorafenib) that block the activity of proteins made by mutant BRAF genes; and MEK inhibitors (trametinib, cobimetinib, binimetinib) that block proteins (MEK1 and MEK2) which affect the growth and survival of cancer cells." (PMID 37896185, 2023). "Unlike BRAF, which is altered in up to 8% of all cancers, RAF1 has a notably lower alteration frequency of 0.7% in cancers." (PMID 38111008, 2023). "As in other cancers, most Class I BRAF alterations occurred in the relative absence of additional oncogenic alterations, suggesting they are the primary oncogenic drivers in these tumors." (PMID 36854806, 2023).
cancer (continued). "The BRAF V600E belongs to the RAS/RAF/MAPK (MEK)/ERK pathway, which is the most important signaling cascade related with proliferation, differentiation and apoptosis, and promotes ERK hyperactivation that is critical in cancer development and progression." (PMID 37446330, 2023). "In our material, it allowed the identification of 92.9% of cancers negative for rFNA, EU-TIRADS and BRAF mutation, including all cancers corresponding to AUS-other nodules and 85.7% of cancers corresponding to AUS-nuclear nodules." (PMID 37686562, 2023). "All seven (100.0%) BRAF- and EU-TIRADS-negative cancers in the AUS-other group and six out of seven (85.7%) such cancers in the AUS-nuclear group could be revealed by a positive result of at least one miRNA." (PMID 37686562, 2023). "BRAF mutations occur early in the process of CRC tumorigenesis, and cancer progression in BRAF-mutant pre-cancerous lesions is unlikely to occur in the absence of other factors such as CIMP." (PMID 38139338, 2023). "In conclusion, BRAFV600E is a common kinase activating alteration in human cancer and in CNS with high prevalence in pLGG, whereby patients with BRAFV600E altered tumors are routinely, successfully treated with molecular targeted therapy (BRAF inhibition)." (PMID 37920169, 2023). "An examination of CERES scores among KRAS, NRAS, and BRAFV600E mutant cancer cell lines indicated that KRAS and NRAS mutant cells had a heightened reliance on CRAF for proliferation, while BRAFV600E mutant cells primarily depended on BRAF for their growth." (PMID 38111008, 2023). "In vitro analysis revealed that the gross cancer cell behaviours, including cell proliferation rates, with or without BRAF inhibitors, or migration/3D invasion potentials, were similar between the original and adapted cells." (PMID 37545523, 2023). "Additionally, we discuss emerging targets in specific cancer subsets, such as mesenchymal-epithelial transition (MET), ROS1, BRAF, and poly(ADP-ribose) polymerase (PARP), that hold promise for further advancing targeted therapies." (PMID 37686423, 2023). "AP-1-clustered sites are present only in the promoter of claudin 4, but the mRNA of this claudin is not upregulated in CMS3 or CMS1 cancers where the KRAS/MAPK pathway is mostly activated due to activating KRAS and BRAF mutations, respectively." (PMID 37998722, 2023). "In a previous study, BRAF and RET/PTC1 rearrangement and TERT promoter mutations were associated with more aggressive cancers than malignancies without one of these mutations." (PMID 37370711, 2023). "Patients without HT and BRAF-mutant carcinomas were more likely to exhibit disease recurrence (44.2% vs. 20.0%, p < 0.001)." (PMID 37190300, 2023). "HT remains a protective factor in BRAF-wild type carcinoma, but not in patients with BRAF-mutant carcinoma." (PMID 37190300, 2023). "Mutations in MAATP53, EGFR, FAT4, KMT2C, ARID1A, FAT1, and RNF213 were observed in the original cancer tissues, whereas KRAS and BRAF mutations were not identified." (PMID 35721089, 2022). "Hitherto, don’t have been reported that the DNMT3B binding in promoters results in an increased gene expression if not quite the opposite, hence, we focus on four downregulated genes with cis elements and functionally related to cancer, PPL1, IRF1, BRAF, and VAV3." (PMID 36460706, 2022). "Autoimmune toxicities, while common following treatment with cancer immunotherapies, are not well-characterized in patients treated with BRAF/MEK inhibitors." (PMID 35433480, 2022). "These include anti-EGFR monoclonal antibodies for KRAS wild type disease, combinations of anti-EGFR monoclonal antibodies with BRAF inhibitors for BRAF mutant cancers, anti-HER2 therapies for HER2 altered cancers and immune checkpoint inhibitors for microsatellite instability (MSI) high cancers." (PMID 36295658, 2022).